APP (amyloid beta precursor protein)
Diseases named in the same sentence as APP in open-access papers (continued):
Sharing a sentence is not in itself a finding about the gene and the disease.
neuroblastoma (continued). "This suggests that SEPTIN5 may additionally affect the trafficking of APP through the secretory pathway in polarized cells, such as neurons, but not in non-polarized neuroblastoma cells." (PMID 33203136, 2020). "However, when we examined the cohort of genes identified using ChIP (chromatin immunoprecipitation)-on-chip in neuroblastoma cells overexpressing AICD and Fe65, we found very limited overlap with our sets of APP copy-number-dependent up- or downregulated genes in DS neurons." (PMID 29861166, 2018). "Moreover, CDX-mediated removal of cholesterol increased membrane fluidity and leads to α-secretase overexpression in neuroblastoma SH-SY5Y cells, whereas, higher levels of mitochondrial APP levels in AD-affected brain areas have been found to correlate with mitochondrial dysfunction." (PMID 29204109, 2017). "APP levels have been reported to be elevated by certain pro-inflammatory conditions in mouse brain and in human neuroblastoma and non-neuronal cells, as well as in human astrocyte cultures, suggesting the potential for amyloidogenic APP processing associated with pro-inflammatory conditions." (PMID 22047170, 2011). "Here, we investigated p23 modulation of APP metabolism and report that diminution of p23 expression in non-neuronal and neuroblastoma cell lines leads to increased biosynthetic stability and maturation of nascent APP, cell surface accumulation of APP, as well as secretion of sAPP." (PMID 17288597, 2007). "It has been shown that melatonin inhibits the formation of soluble APP in vitro, which in turn could prevent Aβ production, consistent with the decrease in APP mRNA level after melatonin administration in P12 cells, but not in human neuroblastoma cells." (PMID 29498103, 2018). "As we could not obtain a selective antibody against TAT, we performed this experiment in a mouse neuroblastoma cell line in which APP is knocked out (N2a-APPKO) to allow selective identification of exogenously applied TAT-AICD-NLS or TAT-AICD-NES using the APP antibody Y188." (PMID 28682239, 2017). "Moreover, interactions between Aβ and sequences within the APP and BACE1 promoters have been reported by the use of Chip assays on human neuroblastoma cells and by electrophoretic mobility shift assays (EMSA) indicating that Aβ peptide may regulate genes involved in its own production." (PMID 24391587, 2013). "For example, when IMR-32 neuroblastoma cells were exposed to 60 Hz at 50, 100, and 200 μT for four hours there were no changes in the expression of APP695, an isoform of APP." (PMID 40084342, 2025). "On the other hand, when IMR-32 neuroblastoma cells were exposed to 60 Hz at 50, 100, and 200 μT for four hours, there were no changes in the expression of APP695, an isoform of APP." (PMID 41221473, 2025). "In SH-SY5Y neuroblastoma cells and primary neurons, JTR-009 functioned as an intercalator to stop ribosome attachment to the precursor transcript, which in turn suppressed APP expression without altering iron homeostasis." (PMID 39770511, 2024). "Next, to investigate if the increase in APP protein levels occurs via p-ERK, we harvested SH-SY5Y neuroblastoma cells without serum reactivation." (PMID 37469955, 2023). "MiR-298 significantly reduced (~ 30%) APP and BACE1 mRNA levels in astrocytes (U373) but not in differentiated neuroblastoma cells (SK-N-SH)." (PMID 35197498, 2022). "MiR-298 reduces APP and BACE1 in one type of human astrocytes U373 but not in human differentiated neuroblastoma or microglia cells." (PMID 35197498, 2022). "When ATRA-differentiated neuroblastoma cultures (NBRA) were treated with miR-20b mimic, APP reduction was not significant." (PMID 35087196, 2022). "Human neuroblastoma SH-SY5Y, mouse neuroblastoma N2a, or non-neuronal CHO cells were transfected with an empty vector (control) or a vector containing full-length, wild-type APP695 (APP)." (PMID 30612335, 2019).
neuroblastoma (continued). "Pretreatment with melatonin resulted in a significant reduction in the APP mRNA level in PC12 cells, but failed to produce this effect in human neuroblastoma cells." (PMID 21358971, 2010). "It is important to note that although our study revealed that APP and ITPKB are novel direct targets for ERβ1 regulation, these studies were performed in an undifferentiated neuroblastoma cell line which might not be directly applicable to human pathology." (PMID 40475329, 2025). "Moreover, it has been demonstrated that 24-OHC inhibits the secretion of Aβ by increasing APP processing via the non-amyloidogenic α-secretase pathway in rat primary neurons and in SH-SY5Y neuroblastoma cells." (PMID 34067119, 2021). "Our results suggest that endogenous APP protein was reduced only in U373 but not HMC3, HeLa or differentiated neuroblastoma cells, and that a full-length APP 3′-UTR activity reporter activity was reduced in differentiated neuroblastoma cells when co-transfected with miR-298 mimics." (PMID 35197498, 2022).
dementia (347 papers, 2005 to 2025). Loss of intellectual abilities interfering with an individual's social and occupational functions. "Of the genes/proteins associated with dementia, six are consistent with the results obtained from VOSviewer: APP, MAPT, APOE, ACE, IL6, and CRP." (PMID 40699836, 2025). "Dimethylguanidino-valeric acid was more strongly associated with dementia risk among carriers of the rs2154481-C allele (APP)." (PMID 40855194, 2025). "For example, amyloid precursor protein (APP), a protein commonly associated with dementia, only indicated significant downregulation relative to NHC in cortical layer I and cortical layers II-V of the cortex but not the subcortical white matter." (PMID 40476255, 2025). "Genetic tests consisted of a 54-gene dementia panel, focusing on Class IV/V variants per American College of Medical Genetics and Genomics guidelines, including APP duplications and the C9ORF72 repeat expansion." (PMID 39869842, 2025). "Targeting APP represents a possibly significant step toward developing precision therapies for DS‐associated dementia, potentially paving the way for more personalized and effective treatment options in this vulnerable population." (PMID 40339155, 2025). "Individuals with DS have a form of genetically determined DS-associated dementia owing to the APP gene dose effect." (PMID 40760500, 2025). "Elevated serum levels of oleic acid, linolenic acid, and linoelaidic acid in APP/PS1 mice align with clinical reports linking these metabolites to dementia risk." (PMID 40860878, 2025). "For instance, cg23393368, a DMC in astrocytes associated with CDR dementia staging, is close to rs4817090, an AD GWAS SNP mapped to gene APP that is important for AD." (PMID 38168620, 2024). "Other proteins include dementia-associated proteins such as amyloid precursor protein (APP) and SQSTM1 protein, a protein associated with ubiquitination." (PMID 39696638, 2024). "Dysregulation of APP expression has been described in AD patients, and Down syndrome (DS) is associated with AD-like dementia due to APP triplication." (PMID 37307834, 2024). "In sum, dementia in DS is mainly caused by increased expression of APP and other genes present in the DS-critical region of chromosome 21 (e.g. DYRK1A)." (PMID 38554150, 2024). "Genetic factors significantly influence the development of dementia, especially mutations in the amyloid precursor protein (APP) and presenilin 1 and 2 genes." (PMID 39585054, 2024). "Genetically, the cause of early onset dementia in DS is a 1.5-fold increase in Aβ production and early Aβ plaque disposition due to the localization of the APP gene on the triplicated chromosome 21." (PMID 38554150, 2024). "Basically, it is known that autosomal cases (i.e., presenilin-1 and 2, APP) linked to AD, the most common cause of dementia, represent a very small percentage of AD cases (≤1%) versus those with a sporadic late-onset disease." (PMID 39064140, 2024). "Phenotypes associated with APP duplications were heterogeneous with different clinical presentations including dementia, hemorrhage, and seizure and different radiological presentations, even within families." (PMID 37170141, 2023). "The introduction of point mutation threonine 668 (T668) to alanine in APP, which precludes phosphorylation, is shown to prevent memory and synaptic impairments in a familial Danish dementia mouse model." (PMID 37387352, 2023). "The disruption of normal signaling function of APP is reported to cause cell cycle abnormalities in neurons and to be associated with neurodegeneration and consequent dementia in DS." (PMID 37740230, 2023). "The pathological effects of APP overproduction are consistent with the high prevalence of AD and associated dementias in people with Trisomy 21, as APP is encoded on chromosome 21." (PMID 36076238, 2022). "BACE2 encodes a glycoprotein that splits APP into AβP, which promotes the amyloid plaque formation in AD and the brain with DS causing dementia." (PMID 35676933, 2022).
dementia (continued). "More comprehensive studies evaluating infection susceptibility and incident dementia rates in APP and PSEN mutation carriers are warranted." (PMID 35517047, 2022). "Diet must also be considered along with excessive intake of glycotoxins, which have adverse effects related to the pathogenesis of dementias such as AD and the metabolism of amyloid precursor protein (APP) and regulatory pathways linked to tau phosphorylation." (PMID 35684025, 2022). "This work provides critical mechanistic insight into the development of disease and an explanation for the typically later age of onset of dementia in people who have AD in DS, compared with those who have familial AD caused by triplication of APP." (PMID 35835549, 2022). "APP locus duplication causes autosomal dominant-early onset AD, and Down syndrome-associated triplication of the APP locus results in early onset dementia." (PMID 34356087, 2021). "Recently, a case of probable CBS was described for the first time in a patient with an APP mutation and a very relevant positive family history for dementia, parkinsonism, and behavioral disorders." (PMID 33467748, 2021). "In this context, it is worth mentioning that several genes linked to dementia, including APP, PSEN1, PSEN2, and ITM2b, play a physiological role in glutamatergic transmission and that mutations linked to familial dementia alter this physiological functions." (PMID 33434745, 2021). "These inherited forms of dementia typically have earlier onset and are caused by high penetrance mutations in multiple loci, including in the amyloid precursor protein (APP) gene, which encodes the protein from which Aß is derived by proteolytic cleavage." (PMID 33522485, 2021). "The most common symptoms of APP mutation carriers in our analysis were cognitive symptoms and/or dementia (almost 98% of cases)." (PMID 34830236, 2021). "Here, we evaluate BMAA exposure by investigating transcription signatures using PCR for dolphin genes homologous to those implicated in AD and related dementias: APP, PSEN1, PSEN2, MAPT, GRN, TARDBP, and C9orf72." (PMID 34678990, 2021). "The high risk of dementia in adults with DS has been attributed, at least in part, to the overexpression of the amyloid precursor protein (APP) located on chromosome 21, which is triplicated in Down Syndrome." (PMID 34279450, 2021). "Dr. Huang's study shows the main clinical features of progressive memory impairment followed by rapid progression to severe dementia within 5–10 years with an AAO of around 46–55 years in Taiwanese patients with the novel APP Asp678His mutation." (PMID 32767553, 2020). "Several mutations (e.g., A02V) induce Aβ overproduction by modulating APP processing, causing amyloid formation and early onset dementia." (PMID 32260279, 2020). "The APP London (V717I) mutation is one of the most common familial APP mutations of AD, with patients experiencing the onset of clinical dementia at an average age of 5964." (PMID 32300132, 2020). "Relevant to our study, epidemiological studies have shown that excessive alcohol consumption is a risk factor for dementia and alcohol intake drives expression levels of amyloid precursor protein (APP) and Aβ-producing enzymes in animal models." (PMID 31829281, 2019). "Synapse losses can be documented with the first clear-cut evidence for dementia that are accompanied by synaptic toxicities conferred by APP and APOE mutations." (PMID 30902061, 2019). "We also analyzed SCRN1 distribution in the brain in HCHWA-D, which is a rare autosomal dominant disorder caused by an APP 693 mutation that clinically leads to recurrent hemorrhagic strokes and dementia." (PMID 31796108, 2019). "Here, we performed a systematic screening of known dementia-causing genes (APP, PSEN1, PSEN2, or GRN genes) in 821 PD cases and 423 controls from North America in addition to 553 PD patients and 550 healthy controls from Spain." (PMID 29692703, 2018).
dementia (continued). "Using clinical and genetic approaches, our findings indicate that mutations in PSEN1 and APP can lead to atypical clinical symptoms at an early stage and a serious form of dementia." (PMID 30090657, 2018). "Two FAD mutations, Tottori and Iowa, are reported to be present in early-onset dementia and to cause the substitution of Asp7 or Asp23, respectively, for the Asn residue in the AβP region of APP." (PMID 30126231, 2018). "While this mutation accelerates amyloid β (Aβ) oligomerization, only patient homozygotes suffer from dementia, implying that this mutation is recessive and causes loss-of-function of amyloid precursor protein (APP)." (PMID 28760161, 2017). "The “critical region” encompasses genes potentially associated with increase risk of dementia, e.g. the APP gene (amyloid beta precursor protein) which leads to excessive amyloid beta production." (PMID 28551695, 2017). "While people with DS and Dup-APP are at high risk of dementia, presumably in both cases because of APP triplication, there are some intriguing differences in their AD-related clinical features." (PMID 26528151, 2015). "Accordingly, we report here that the alteration in APP binding to SorLA (and likely to other adaptors) leads to APP accumulation in LEs and lysosomes and to autophagic defects, which are considered a major risk factor for AD and dementia during aging." (PMID 25904844, 2015). "Mutations in amyloid precursor protein (APP) are observed in patients with familial early-onset AD or dementia caused by cerebral amyloid angiopathy." (PMID 25312309, 2014). "Recently, a number of single nucleotide polymorphisms (SNPs) located in the 3'UTR of APP have been found in AD patients with family history of dementia." (PMID 21982160, 2011). "Mutations in the APP gene can lead either to AD or to hemorrhagic stroke and dementia (as in HCHWA-D) depending on the site of the mutation and the subsequent cellular site of amyloid accumulation." (PMID 19895675, 2009). "For instance, APP A713T mutation near the γ-secretase site reportedly leads to progressive dementia and multiple strokes, and pathological studies confirm AD with severe CAA with multiple infarcts in brain." (PMID 19468344, 2009). "Soon after, the Flemish APP mutation replacing a glycine (G) by an alanine (A) at the adjacent codon 692 was identified in another Dutch family suffering from presenile dementia and cerebral haemorrhage inherited in an autosomal dominant pattern." (PMID 19468344, 2009). "A neuropathological examination revealing extensive beta-amyloid positive CAA with ICH, can also be an indicator of on an underlying CNV in APP, and we emphasize that individuals with a clinical diagnosis of (early onset) dementia are offered neuropathological examination postmortem." (PMID 39849058, 2025). "Our data suggests that expression of dementia-causing genes (APP, PS1, Tau) is sufficient to cause peripheral metabolic deficits including increased adiposity and diabetes-like changes in glucose handling and that occur in the absence of changes in dietary or environmental factors." (PMID 38565895, 2024). "There were no genome-wide or suggestive associations with genetic variants in known causal Mendelian dementia genes (APP, PSEN1, PSEN2, and GRN), suggesting that common variants in these genes do not significantly contribute to sporadic EOAD, or that we do not have enough power." (PMID 38883718, 2024). "Some molecular mechanisms explained the pathological development of early-onset dementia progression, including mutations in the amyloid precursor protein (APP) gene, as well as presenilin 1 or 2 (PS1 or PS2) genes, which are closely related to the early onset of dementia." (PMID 39350383, 2024). "The increased risk for dementia in individuals with DS is associated with trisomy of the APP gene." (PMID 37015911, 2023).